ALB (albumin)
Diseases named in the same sentence as ALB in open-access papers (continued):
Sharing a sentence is not in itself a finding about the gene and the disease.
Hypoalbuminemia (continued). "Higher serum albumin levels have been associated with decreased risk of diabetic retinopathy and diabetic kidney disease, while hypoalbuminemia (serum albumin level < 3 g/dL) was significantly associated with higher prevalence of ketonuria compared to those with normal albumin levels." (PMID 35807807, 2022). "Another possible explanation for high TG levels and lower ALB levels is medical comorbidities, especially hypertriglyceridemia and hypoalbuminemia, which might cause functional impairment." (PMID 36203826, 2022). "Given the anti-inflammatory and antioxidant biochemical properties of serum albumin, we speculate that hypoalbuminemia could act as an important modifiable risk factor for AF." (PMID 36031606, 2022). "However, some studies found that the use of HCO membranes was associated with a large amount of albumin loss and even clinical hypoalbuminemia, which limited their routine application in chronic hemodialysis." (PMID 35323729, 2022). "In addition, patients who managed to normalize their serum albumin levels and did so in an early manner, even with initial postoperative hypoalbuminemia, had a fivefold lower risk of complications." (PMID 33875388, 2022). "Hypoalbuminemia was associated with long-term protein dystrophy in chronic HF, and albumin may have been further affected by the inflammatory status in patients with ADHF." (PMID 36371183, 2022). "Because hypoalbuminemia is also a strong predictor of adverse clinical outcomes in patients undergoing dialysis, how to balance the relation between serum phosphorus and albumin and their interactive impacts on mortality risk remains a clinical conundrum." (PMID 34926505, 2021). "Lastly, serum ALB level has been used classically as a biomarker of protein nutritional status, with the level < 35 g/L defined as hypoalbuminemia, but low serum ALB level is currently viewed more as a risk factor and a predictor of morbidity/mortality regardless of the implicated diseases." (PMID 33804859, 2021). "Albumin has been shown to have an important impact on survival and several papers demonstrate that albumin is an important prognostic parameter of clinical outcome: low serum albumin levels (hypoalbuminemia) are associated with increased risk of HF onset and progression." (PMID 33673523, 2021). "Hypoalbuminemia is often due to inflammation but can also be caused by hepatocyte damage and decreased albumin synthesis, dietary insufficiency of amino acids, or increased excretion of albumin." (PMID 33925831, 2021). "Second, because HDL was associated with the lower albumin tertile, this lipid marker could be important to predict hypoalbuminemia in candidates, and therefore these patients could be considered to receive nutritional support." (PMID 35010957, 2021). "Although the distribution of hs-CRP was different among ACS and stable CAD patients, the increased risk relation of combined hs-CRP to albumin was consistent, which may rely on the mechanism of inflammation in hypoalbuminemia." (PMID 34961476, 2021). "Hypoalbuminemia is associated with the severity of different kinds of infections, including those caused by Pseudomonas aeruginosa, Clostridium difficile, and influenza, and albumin levels are predictive of infection complications as shown in scrub typhus." (PMID 33925831, 2021). "Hypoalbuminemia may be a factor favoring thrombosis but an interventional trial with albumin supplementation is needed to establish a cause-effect relationship." (PMID 34218413, 2021). "Regarding hypotension, albumin has long been known to be the primary driver of oncotic pressure in vascular tissue and hypoalbuminemia is known to cause fluid extravasation and edema; thus, the finding of an association here between hypoalbuminemia and hypotension is not surprising." (PMID 33986318, 2021).
Hypoalbuminemia (continued). "Maintaining the level of albumin in blood is essential for all dialysis membranes, as excessive albumin loss could trigger albumin loss syndrome (hypoalbuminemia), which could result in morbidity for the patients and even death." (PMID 34677533, 2021). "Hypoalbuminemia leading to an increased risk of peritonitis could be attributed to the albumin-related inhibition of apoptosis of peritoneal macrophages." (PMID 34233593, 2021). "For children aged between 1 year and 2 years, hypoalbuminemia (ALB < 35 g/L) was the only independent risk factor associated with an increased risk of developing severe CAP, while low birth weight and proteinuria were the only two independent risk factors for ICU admission." (PMID 33892752, 2021). "The reason for hypoalbuminemia in T2DM may be multiple including loss of albumin for concomitant kidney disease, liver disease or infections." (PMID 34239442, 2021). "Serum albumin is typically used as an indicator of the nutritional status of patients, although hypoalbuminemia may also be associated with inflammation." (PMID 34233593, 2021). "Wiedermann indicated that preexisting hypoalbuminemia contributes to the risk of acute infectious diseases, and that acute loss of albumin in systemic inflammatory reactions further complicates the clinical course of all trauma, medical, and surgical conditions." (PMID 34961476, 2021). "Decreased serum ALB levels were significantly associated with eGFR decline, and hypoalbuminemia may be related to proteinuria or underlying inflammation." (PMID 34300251, 2021). "Prospective studies are needed to analyze whether prevention of hypoalbuminemia (e.g., by optimizing nutrition or replacing albumin) can minimize the risk for AKI in AML patients undergoing induction chemotherapy." (PMID 33704529, 2021). "Albumin is a potential natural antioxidant that acts as a core extravascular source of reduced sulfhydryl groups, so-called thiols, that scavenge reactive oxygen and nitrogen species; thus, hypoalbuminemia can cause postoperative AKI." (PMID 33916162, 2021). "Some theories exist regarding the reasons why lower serum albumin levels, or hypoalbuminemia, may be associated with poor outcomes." (PMID 34691782, 2021). "In addition to increased kynurenine levels, hypoalbuminemia can also cause a high Kyn/Trp ratio, because less albumin will be available to bind tryptophan, and consequently the plasma concentration of free tryptophan will increase." (PMID 34884980, 2021). "In this study, hypoalbuminemia was also associated with inflammation, but little is known about the relationship between the prognosis and severity of the disease, inflammation and lower levels of albumin in COVID-19 patients." (PMID 32722020, 2020). "Serum albumin was measured at hospital admission after the diagnosis of pulmonary embolism so it is hard to differentiate whether hypoalbuminemia is a cause or a consequence of the thromboembolic process." (PMID 31936687, 2020). "These injuries may also cause leakage of albumin through the inflamed gut wall into the lumen, which may explain the hypoalbuminemia in all infected horses." (PMID 32350359, 2020). "As of this present moment, there is paucity of data on report concerning the association between hypoalbuminaemia or reversal of albumin-to-globulin ratio and morbidity outcome in Lassa fever (LF) infection as a crucial determinant prognostic-predictor factor for treatment-survival outcome." (PMID 33312698, 2020). "Albumin levels reflect nutritional status and organ function, and the underlying inflammatory state give rise to a decrease of albumin production in liver by increasing inflammatory factors, the primary cause of hypoalbuminemia that occurs early in sepsis." (PMID 32238212, 2020).
Hypoalbuminemia (continued). "Albumin infusion was associated with a lower risk of in-hospital rebleeding in pateints with hypoalbuminemia, Moreover, in Child-Pugh C class, albumin transfusion might be correlated with a decreased number of in-hospital deaths." (PMID 32576140, 2020). "The peritoneal albumin loss is an important factor of hypoalbuminemia in PD22." (PMID 31661541, 2020). "Of note, decreased albumin concentration may also be the result of decreased protein production due to hepatic dysfunction and hypoalbuminemia caused by critical illness." (PMID 32234065, 2020). "Although preparations containing ALB can increase albumin levels, the physicians in charge followed the guidelines regarding such preparations when treating patients with sepsis-associated hypoalbuminemia." (PMID 32778146, 2020). "In contrast, it has been reported that persistent proteinuria, which could lead to hypoalbuminemia as a consequence of albumin loss, as well as the serum albumin level itself, were indicative of renal outcomes in LN." (PMID 31252552, 2019). "Hypoalbuminemia is an important factor that causes a dissociation between the Na–Cl level and the serum bicarbonate level, as the AG decreases to 2.5 mmol/L when the serum albumin level decreases to 1 mmol/L." (PMID 30168046, 2019). "A previous study from Japan also found that the serum albumin level was independently associated with proteinuria in Japanese DN patients, and another study examined the impact of hypoalbuminemia on the progression of kidney disease among 343 Caucasian (77%) and black patients with DN." (PMID 30911552, 2019). "In the univariate analysis, patients with hypoalbuminemia (albumin < 3.5 g/dL) had an increased risk of delayed wound healing (39.5% vs. 60.5%, P = 0.001), which was an independent risk factor in the multivariable analysis (OR 2.962, 95% CI 1.437–6.102, P = 0.003)." (PMID 31864365, 2019). "Furthermore, we explored factors associated with hypoalbuminemia and changes in albumin levels during hospitalization." (PMID 31095609, 2019). "The association between the preoperative albumin level and kidney injury has been investigated in coronary bypass surgery, mostly regarding the use of the off-pump technique, and preoperative hypoalbuminemia has been shown to be a major risk factor for AKI in off-pump CABG surgery." (PMID 30971264, 2019). "We report the case of a 71-year old woman who developed severe hypoalbuminemia resulting from massive albumin loss during dialysis while treated by high-volume post-dilutional OL-HDF with a large surface steam sterilized polyphenylene HF dialyzer, the Phylther HF20SD (Bellco)." (PMID 31660886, 2019). "Preoperative serum ALB reflects nutritional status; it decreases in response to systemic inflammation during malignant tumor growth, leading to hypoalbuminemia and weight loss, which may in turn affect the immune system of the cancer patients." (PMID 31355160, 2019). "Hypoalbuminemia is also highly prevalent among HD patients (25-50%) and also associated with high morbidity and mortality 34, and a greater risk of mortality noted particularly when serum albumin <3.8 g/dL 40-42." (PMID 31839746, 2019). "Renal loss of albumin can lead to hypoalbuminemia which was seen in 5/6 dogs in our study." (PMID 30073173, 2018). "Low serum albumin concentration is a risk factor for and a predictor of morbidity and mortality, regardless of the disease, and a relationship exists between hypoalbuminemia and severe infection due to the elevation of cytokine levels during systemic inflammation." (PMID 29382316, 2018). "Besides, since zinc is transported by albumin, serum levels below normalitycan be found in some conditions associated with hypoalbuminemia, such asprotein-energy malnutrition." (PMID 29412435, 2018). "In addition to inflammation, peritoneal albumin loss and volume overloading can lead to hypoalbuminemia in patients on PD." (PMID 29694445, 2018).
Hypoalbuminemia (continued). "Some theories exist regarding the reasons that lower serum albumin levels, or hypoalbuminemia, may be associated with poor outcomes." (PMID 30423847, 2018). "Hypoalbuminemia may be caused by cytokines which is released by the tumor cell, such as interleukin(IL)-6, which blocks hepatocyte albumin production." (PMID 28978171, 2017). "Nutritional malfunction suppresses albumin synthesis, causing hypoalbuminemia, which may have an adverse effect on the overall effectiveness of TKIs in mRCC patients and may result in poor survival outcomes." (PMID 28521783, 2017). "Considering that hypoalbuminemia is also a frequent finding in chronic disease, data from predominantly community-acquired sepsis suggested that hypoalbuminemia is related to infection and showed that albumin can serve as an independent risk parameter." (PMID 28869492, 2017). "The significantly lower serum albumin concentration in our IBS cohort suggests that hypoalbuminemia may play a role in the pathogenesis of vitamin D deficiency in IBS in children and adolescents." (PMID 28192499, 2017). "Factors that may contribute to hypoalbuminemia include exogenous loss of albumin, albumin re-distribution, catabolism rate of proteins, and inflammation; these factors may explain the association of hypoalbuminemia with SCD." (PMID 29117224, 2017). "Moreover, intracellular albumin and glutamate levels are increased by the loss of FcRn-mediated recycling of albumin, combined with hypoalbuminemia in tumor-bearing mice." (PMID 27974681, 2017). "In clinical practice, an association between hypoalbuminemia and insulin deficiency may explain the increased mortality rate in hyperglycemic individuals with low serum albumin concentration." (PMID 27504458, 2016). "Hypoalbuminemia associated with large urinary losses of protein, which decreases albumin levels, may also be associated with albumin modification and variability in the measurements by BCG." (PMID 27453993, 2016). "There are two albumin related diagnostic predictors of pleural effusion and/or ascites, i.e., the lowest albumin concentration at the critical phase (≤3.49) and the degree of hypoalbuminemia (>15.6 %)." (PMID 27391122, 2016). "In patients who are undergoing PD, protein losses in the urine and PD fluid can significantly cause hypoalbuminemia; as such, we can hypothesize that GA levels can be underestimated because of the shortened exposure time of serum albumin to glucose in plasma." (PMID 27120597, 2016). "In DHF, hypoalbuminemia results from the loss of albumin due to the occurrence of plasma leakage." (PMID 27391122, 2016). "In an outpatient setting, serum albumin concentration was found to be inversely associated with HbA1C, suggesting that hypoalbuminemia may reflect insulin deficiency and subsequent hyperglycemia." (PMID 27504458, 2016). "Yet, COP may be used potentially as a tool for "differential diagnosis" between true hypoalbuminemia states that originate from decreased albumin production or albumin loss to those originating from decreased detection." (PMID 27453993, 2016). "Low level of serum albumin also reflects the state of malnutrition and inflammation, thus the implication of hypoalbuminemia may serve as a multifactorial risk factor in CKD progression." (PMID 26177463, 2015). "In acutely ill patients, hypoalbuminemia has been strongly associated with poor clinical outcomes, including morbidity, mortality, and prolonged hospital stays and it has been advocated that albumin levels be monitored in these patients." (PMID 25674854, 2015). "Although further in vivo studies using analbuminemia rats are necessary to demonstrate the inhibition of carcinogenesis by albumin, the present study provides the first data to support the clinical observations that hypoalbuminemia is associated with a tendency to develop hepatocellular carcinoma." (PMID 24663086, 2014).
Hypoalbuminemia (continued). "The level of serum albumin was found decreased, where the levels in severe cachectic mice were significantly lower (P<0.05, CancerModerate vs. CancerSevere) than those of moderate, suggesting hypoalbuminemia is closely associated with weight loss." (PMID 23349693, 2013). "Given this strong association between hypoalbuminemia and patient outcomes, an intervention that successfully improves serum albumin levels may exert substantial effects on overall patient health and survival." (PMID 24967248, 2013). "High proteinuria levels are associated with hypoalbuminemia, which may be associated with decrease in peritoneal albumin loss." (PMID 23245677, 2012). "In transplanted patients, urine heparanase/creatinine was significantly associated with urine protein/creatinine (p<0.006), and significantly inversely associated with serum albumin (p<0.02), suggesting a causal effect of heparanase in the development of proteinuria and hypoalbuminemia." (PMID 23028487, 2012). "Albumin showed the strongest effect among laboratory markers, both as a continuous measure (HR 1.18 per 0.1 g/dL decrease, p < 0.001) and as a categorical variable (<3.5 g/dL; HR 2.11, p < 0.001), indicating a substantial increase in risk among patients with hypoalbuminemia." (PMID 41517580, 2026). "Notably, hypoalbuminemia appears to be a protective factor against pDDIs, with patients in the hypoalbuminemia group having only 0.24 times the risk of pDDIs compared to those with normal albumin levels." (PMID 41601964, 2026). "Notably, hypoalbuminemia emerged as an independent risk factor for disease severity, which may be linked to the increase in vascular endothelial permeability, ALB exudation, and Hb consumption caused by infection." (PMID 41476735, 2025). "Cytokine-mediated peripheral albumin degradation and decreased oral intake leading to relative protein deficiency have both been specifically attributed to patients with advanced cancer, in which hypoalbuminemia has been explored as a clinical biomarker for many years." (PMID 40103850, 2025). "Hypoalbuminemia has been consistently associated with unfavorable clinical outcomes, a relationship that may be mechanistically explained by the suppression of hepatic albumin synthesis during inflammatory states." (PMID 41492631, 2025). "Since cardiopulmonary bypass is also known to induce increased inflammatory responses and cytokine levels, hypoalbuminemia may also be associated with increased risk because low albumin levels may weaken immune defenses at the cellular level, making patients more susceptible to infections." (PMID 39857079, 2025). "Therefore, hypoalbuminemia may be a risk factor for CI, while increasing albumin levels may contribute to improved cognitive function." (PMID 41163373, 2025). "Although our study focused on serum albumin as a specific marker of endothelial dysfunction and capillary leakage, the lack of total protein data limits the ability to assess whether hypoalbuminemia reflected a selective albumin loss or a more generalized reduction in circulating proteins." (PMID 40648856, 2025). "Importantly, not only albumin replacement therapy but also management of the underlying conditions contributing to hypoalbuminemia may help reduce mortality." (PMID 41303773, 2025). "Given that hypoalbuminemia is a common finding in chronic disease, data from community-acquired sepsis studies have suggested that hypoalbuminemia is associated with infection and have shown that albumin may serve as an independent risk parameter." (PMID 40868186, 2025). "In hypoalbuminemia there is a higher unbound proportion of chemotherapeutic drugs and increased time of drug’s clearance causing delayed elimination–that may be reasons why patients with lower level of albumin developed more adverse reactions." (PMID 40051558, 2025).